NOTCH1 (notch receptor 1)
Diseases named in the same sentence as NOTCH1 in open-access papers (continued):
Sharing a sentence is not in itself a finding about the gene and the disease.
Myocardial fibrosis (12 papers, 2014 to 2026). "Several publications have highlighted the protective role of the Notch1 pathway in averting myocardial fibrosis." (PMID 39850112, 2025). "NOTCH1 inhibition decreased myocardial fibrosis and infarction area, while EZH2 inhibition increased fibrosis." (PMID 39951437, 2025). "Many studies have suggested that activation of the Notch1 signaling pathway prevents myocardial fibrosis." (PMID 35273164, 2022). "Numerous studies have confirmed that Notch1 upregulation inhibited myocardial fibrosis in animal MI models whereas, Notch1 inhibition worsened cardiac dysfunction by increasing myocardial fibrosis in both MI injured hearts and in diabetic heart." (PMID 34957094, 2021). "FSTL1 treatment significantly reduced myocardial fibrosis and improved cardiac function by activating the Notch1 signaling pathway, which was reversed by Notch1 inhibitor." (PMID 34957094, 2021). "Our present study revealed that FSTL1 protected cardiac function against MI-induced myocardial fibrosis in T2DM through a USP10/Notch1-dependent mechanism." (PMID 34957094, 2021). "Further in vitro analysis provided evidence that FSTL1 activated USP10/Notch1 signaling to inhibit myocardial fibrosis." (PMID 34957094, 2021). "A recent study indicated that activation of Notch 1 limits the extent of ischemic damage, reduces myocardial fibrosis, and improves heart function." (PMID 30065940, 2018). "NOTCH1 inhibition decreased DLBCL cell proliferation and activity, reduced inflammatory factors, and improved myocardial fibrosis and infarction severity." (PMID 39951437, 2025). "Moderate physical activity inhibits myocardial fibrosis by expressing Notch1 cardiac genes, the FSTL1-USP10-Notch1 signaling axis." (PMID 36036015, 2022). "The present study employed both in vivo and in vitro experiments to decipher the changes in Notch1 and USP10 and to evaluate the possible interaction between FSTL1 and USP10 in the pathological mechanism of MI-induced myocardial fibrosis in T2DM." (PMID 34957094, 2021). "In conclusion, FSTL1 treatment ameliorated cardiac dysfunction in MI with co-existent T2DM, possibly through inhibition of myocardial fibrosis and apoptosis by upregulating USP10/Notch1 signaling." (PMID 34957094, 2021). "Moreover, our results establish a crosstalk between USP10 and Notch1 in the inhibition of myocardial fibrosis and improvement in cardiac function by alleviating adverse remodeling against MI injury in T2DM and may provide better prognosis for T2DM patients with MI." (PMID 34957094, 2021). "In addition, in specific models of “MI plus type 2 diabetes,” exogenous supplementation or overexpression of FSTL1 reduced myocardial fibrosis and improved cardiac function through the USP10/Notch1 axis." (PMID 41602834, 2026). "Notably, mice lacking Notch1 displayed myocardial fibrosis following myocardial injury in contrast to their wild-type counterparts." (PMID 39850112, 2025).
nasopharyngeal carcinoma (12 papers, 2015 to 2025). A carcinoma arising from the nasopharyngeal epithelium. "ALYREF also stabilizes NOTCH1 mRNA in an m5C-dependent manner, activating the Notch signaling pathway and directly driving the metastasis of nasopharyngeal carcinoma (NPC)." (PMID 41446042, 2025). "Circ_NOTCH1 silencing inhibits the migration of nasopharyngeal cancer cells, where c-Myc can bind to the NOTCH1 promoter to transcriptionally activate circ_NOTCH1." (PMID 36230902, 2022). "In addition, DNER acts as a ligand for Notch1, activating the Notch signalling pathway, and the knockdown of Notch1 expression can inhibit the migration and invasion of nasopharyngeal carcinoma cells by reversing EMT32." (PMID 32811806, 2020). "Importantly, overexpression of Notch-1 promoted cell growth and invasion, whereas down-regulation of Notch-1 inhibited cell growth and invasion in nasopharyngeal carcinoma cells." (PMID 28977931, 2017). "Strikingly, our study implied that Notch-1 could be a useful target of rottlerin for the prevention and treatment of human nasopharyngeal carcinoma." (PMID 28977931, 2017). "The aims of our current study were to explore whether rottlerin could suppress Notch-1 expression, which leads to inhibition of cell proliferation, migration and invasion in nasopharyngeal carcinoma cells." (PMID 28977931, 2017). "Moreover, the expression of Notch-1 was obvious decreased in nasopharyngeal carcinoma cells after rottlerin treatment." (PMID 28977931, 2017). "It has been shown that the circRNA circ-NOTCH1 plays an important regulatory role in the cell proliferation process of nasopharyngeal carcinoma (NPC) by targeting the miR-34c-5p/c-Myc axis." (PMID 36483049, 2022). "Our study suggests that rottlerin could be a new inhibitor of Notch-1 in nasopharyngeal carcinoma." (PMID 28977931, 2017). "Since Notch-1 could be an effective target to treat nasopharyngeal carcinoma, development of Notch-1 inhibitors is important for the treatment of NPC." (PMID 28977931, 2017). "Changes in neurogenesis are followed by decreased expression of Notch1, NICD, and Hes5 in the context of the pathogenesis of PD, suggesting that accumulation of–synuclein may impede nasopharyngeal carcinoma (NPC) survival by impairing the Notch signaling system." (PMID 37600520, 2023).
Tetralogy of Fallot (12 papers, 2014 to 2024). A congenital cardiac malformation comprising pulmonary stenosis, overriding aorta, ventricular septum defect, and right ventricular hypertrophy. "Deletion of the whole NOTCH1 gene was previously reported to cause non-syndromic Tetralogy of Fallot and HLHS." (PMID 33898534, 2021). "NOTCH1 variant carrier, JM1357, has a diagnosis of APAH-CHD with tetralogy of Fallot, and a recent exome sequencing study of ~ 800 tetralogy of Fallot cases identified NOTCH1 as the top association signal." (PMID 33971972, 2021). "In human, mutations of the Notch1 gene are associated with mitral valve anomalies, bicuspid aortic valve disease and tetralogy of fallot." (PMID 24969754, 2014). "The NOTCH1 and FLT4 genes are the genes most frequently implicated in the etiology of the tetralogy of Fallot, with their variants accounting for almost 7% of all cases." (PMID 36496429, 2022). "Null mutants of Notch1 exhibit Tetralogy of Fallot, pulmonary stenosis, atrio-VSD, coarctation of the aorta, hyperplastic left heart syndrome, and left ventricular OFT malformations." (PMID 35736367, 2022). "Pathogenic and likely pathogenic NOTCH1 genetic variants explain 2% of familial and <0.1% of sporadic BAV disease and are more likely to associate with tetralogy of Fallot and hypoplastic left heart." (PMID 35288444, 2022). "NKX2-5, NOTCH1 and GATA4 have high confidence for nonsyndromic CHD, atrial septal defect (NKX2-5 and GATA4), aortic valve stenosis and tetralogy of fallot (NOTCH1)." (PMID 39567769, 2024). "The Endo_EC gene cluster had nine genes, including Notch1 and Foxc2 (Fig. 6Bii), which expressed at all stages and were preferentially related to Hypoplastic Left Heart Syndrome (HLHS), Bicuspid Aortic Aalve (BAV), and Tetralogy of Fallot (TOF)." (PMID 36575170, 2022). "For example, except for the common disease gene JAG1 between Tetralogy of Fallot and Alagille syndrome, the two diseases interact through 5 PPIs with a p value < < 0.01 in the network, including JAG1 – NOTCH1, JAG1 – NOTCH2, JAG1 – NOTCH3, DLL1 - NOTCH2 and DLL1 – NOTCH3." (PMID 25539592, 2014).
thymic lymphoma (12 papers, 2009 to 2025). "This suggests that although genomic instability can originate from different signaling defects at different developmental stages of T cells, loss of functional PTEN and NOTCH1 is often selected to drive thymic lymphoma development." (PMID 32139898, 2020). "C8, C11, C7, and C18 were proximal to double‐positive T cells, representing thymic lymphoma characterised by elevated expression levels of genes like Notch1, Hes1 and Desi1,72, 73 along with markers associated with thymic T‐cell development such as Rag1/2, Xrcc6 and Dntt74." (PMID 40887856, 2025). "Analysis of the panel of 40 Tcf1−/− thymic lymphomas demonstrated mutations in exon 34 in all but one thymic lymphoma sample (unpublished data), which is known to promote Notch1 signaling by increasing the half-life of intracellular Notch, hence promoting tumor survival and growth." (PMID 23185135, 2012). "In the thymic lymphomas, this discordance is evident in the persistent expression of Notch1, Hes1 and p21, as well as the persistent expression of Ikaros isoforms normally seen in the DN3 stage." (PMID 37160922, 2023). "As regards the interaction of HMGA proteins with NOTCH1 signaling, studies on mouse thymic lymphomas detected both the overexpression of HMGA1 and the activation of NOTCH1 signaling." (PMID 32503270, 2020). "Quantitative RT-PCR confirmed that c-myc mRNA expression was negatively correlated with FIR mRNA expression but positively correlated with Notch1 mRNA in sorted T-ALL/thymic lymphoma cells." (PMID 25671302, 2015). "It was found that all primary and secondary Fli-1 pre-T LBL as well as a radiation-induced thymic lymphoma contained type 1 5′ Notch1 deletions." (PMID 23667468, 2013). "As a positive control for Deltex1 and Hes1 expression, we used the immature DN S49 thymic lymphoma cells (lane 5) that endogenously express Bcl-2 and active Notch1." (PMID 22319533, 2012). "Among the thymic lymphomas, we found Pten and Notch1 to be recurrently altered." (PMID 34771656, 2021). "Notch1 mRNA expression in sorted thymic lymphoma cells was confirmed using qRT-PCR." (PMID 25671302, 2015). "In addition, flow cytometry revealed that c-myc mRNA was negatively correlated with FIR but positively correlated with Notch1 in sorted T-ALL/thymic lymphoma cells." (PMID 25671302, 2015).
anaplastic thyroid carcinoma (11 papers, 2014 to 2025). "As a compelling proof-of-concept in cell culture models, resveratrol has been shown to induce redifferentiation markers, including NIS, in anaplastic thyroid carcinoma cells by activating Notch1 signaling." (PMID 40943396, 2025). "It induces the expression of differentiation markers (TTF1, TTF2, Pax8, and sodium/iodide symporter (NIS)) in anaplastic thyroid carcinoma through the activation of Notch1 signaling, thereby suppressing cell growth." (PMID 40943396, 2025). "Resveratrol, for example, has been shown to induce redifferentiation markers (TTF1, TTF2, Pax8, NIS) in anaplastic thyroid carcinoma cells through the activation of Notch1 signaling." (PMID 40943396, 2025). "On the contrary, some research revealed that resveratrol repressed cell growth and enhanced redifferentiation of anaplastic thyroid carcinoma cells through the activation of Notch1 signaling." (PMID 38702698, 2024). "Involvement of VEGF-A with other proliferation regulatory genes such as Notch1 and Bcl-2 has been reported in anaplastic thyroid carcinoma." (PMID 30544959, 2018). "Notch1 signaling was significantly down-regulated in human anaplastic thyroid carcinoma compared with normal thyroid cells, over-expression of Notch1 reduced cancer cells growth and restored differentiation." (PMID 25887589, 2015). "RSV suppressed anaplastic thyroid carcinoma cell growth via S-phase cell-cycle arrest and apoptosis; it induced functional Notch1 protein expression and activated the pathway by transcriptional regulation." (PMID 25276125, 2014). "As knockdown of Nrf2 reduced the metastatic and invasive ability of anaplastic thyroid cancer cells by inhibiting the Notch 1 signaling pathway and increased the cancer cell sensitivity to lenvatinib, Nrf2 could be a promising therapeutic target for patients with anaplastic thyroid cancer." (PMID 34527171, 2021). "Additionally, Notch1 activation also induced cellular differentiation in anaplastic thyroid cancer." (PMID 26563263, 2015). "Notch1 inhibition through Hes5 has been reported to significantly suppress cell migration and EMT in anaplastic thyroid carcinoma." (PMID 41315239, 2025). "Chrysin-treated anaplastic thyroid cancer (ATC) tumors revealed increased protein levels of Notch1 and Hes1 (hairy/enhancer of split 1), and activated Notch1 might induce cleaved Poly ADP ribose polymerase (PARP) protein, indicating that apoptosis could be induced to inhibit cancer cells." (PMID 36678588, 2023).
COVID-19 (11 papers, 2020 to 2025). A disease caused by infection with severe acute respiratory syndrome coronavirus 2. "Notch4 was similarly upregulated on circulating Tregs of pediatric patients with acute COVID-19, while both Notch4 and Notch1 were upregulated on those of patients with MIS-C." (PMID 36282598, 2023). "Hub proteins for post-COVID-19 individuals included cytastatin 3 (CST3), Notch homolog 1, translocation-associated (NOTCH1), complement factor H-related 5 (CFHR5), and ST6 beta-galactoside alpha-2,6-sialyltransferase 1 (ST6GAL1)." (PMID 36405747, 2022). "To further explore the tissue-specific effect of NOTCH1-4 expression on COVID-19, we performed an MR analysis using the tissue eQTL from GTEx V8." (PMID 35602207, 2021). "The recent promising outcome of anti-IL-6 monoclonal antibodies therapy in COVID-19 patients supports the conclusion of this study that Notch-1/IL-6 signaling is key to understand and treat inflammation." (PMID 33072191, 2020). "LEF1 and Notch 1 were able to distinguish severe from mild COVID-19 in the CD8 subset." (PMID 38702425, 2024). "Whereas acute-COVID-19 severity and outcome were previously correlated with Notch4 expression on regulatory T (Treg) cells, here we show that the Treg cells in MIS-C are destabilized in association with increased Notch1 expression." (PMID 35441180, 2022). "Among NOTCH1-4, only NOTCH2 significantly (P = 0.007) increased during aging, suggesting that the age-related increase of COVID-19 risk may partially be mediated through the increase in NOTCH2 expression." (PMID 35602207, 2021). "We propose that miR-146a rs2910164 GC through Notch-1 upregulation causes excessive secretion of IL-6 which may then affect cellular uptake of SARS-CoV-2, development of COVID-19, and contribute to the cytokine storm in patients." (PMID 33072191, 2020). "However, another study warns against anti-TNF-α therapy in COVID-19 patients as it could augment the SARS-CoV-2 receptor and increase the risk of infection through Notch-1 signaling." (PMID 39745465, 2025). "Whereas acute-COVID-19 severity and outcomes were previously correlated with Notch4 expression on Tregs, here, we show that Tregs in MIS-C were destabilized through a Notch1-dependent mechanism." (PMID 36282598, 2023). "Patients with MIS-C, but not children or adults with acute COVID-19, demonstrated increased Notch1 expression on circulating CD4+ Tregs and Tconv cells, all of which declined precipitously following antiinflammatory therapy." (PMID 36282598, 2023). "Increased expression of integrin β7 (ITGB7) was also observed on the circulating Tregs of patients with MIS-C, but not on those of pediatric patients with acute COVID-19, in agreement with a critical role of Notch1 in driving the expression of this marker." (PMID 36282598, 2023). "Notably, our identification of H3-5/H3F3C, H3C13/HIST2H3D, JUN, EGR1, NOTCH1, and SQSTM1/P62 as central hub genes unique to the COVID-19 signature links this pro-oncogenic state to a specific molecular target that regulates inflammation, autophagy, and cancer progression." (PMID 41472277, 2025). "Note that due to the limited number of available eQTLs, we could not perform MR-Egger and simple median method on NOTCH1 and critical illness of COVID-19." (PMID 35602207, 2021). "Hence, the ability of 2-pyridone PIM1 inhibitor to normalize the expression of Notch 1 and reduce the expression of Notch 2 below the control levels could provide a mechanism by which 2-pyridone PIM1 inhibitor could be effective in treatment of COVID-19." (PMID 37211584, 2023). "In contrast, CD22 was minimally expressed on CD4+ Tconv cells of control individuals, patients with acute COVID-19, and patients with MIS-C, and it did not correlate with Notch1 expression in these cells." (PMID 36282598, 2023).
endothelial dysfunction (11 papers, 2015 to 2025). In vascular diseases, endothelial dysfunction is a systemic pathological state of the endothelium (the inner lining of blood vessels) and can be broadly defined as an imbalance between vasodilating and vasoconstricting substances produced by (or acting on) the endothelium. "In contrast, the development of AVMs likely arises from a combination of endothelial dysfunction due to Notch1 heterozygosity, in addition to mural cell dysfunction caused by combined deficiency of Notch1 and Notch3." (PMID 26563570, 2015). "Endothelial dysfunction may be associated with a decrease of Notch1." (PMID 34447638, 2021). "Consistent with reports implicating Notch1-JAG signaling in pathological vascular remodeling and inflammatory responses, these results suggest that targeting Notch1 activation could be an effective strategy for stiffness-induced endothelial dysfunction." (PMID 41278992, 2025). "Moreover, previous studies have demonstrated that Notch1 enhances IL-1β expression and elevates endothelial permeability, thereby precipitating endothelial dysfunction in human brain microvascular endothelial cells." (PMID 40290868, 2025). "Then, NOTCH1, PPARG, NOS3, KEAP1, CDKN2A, and IRS1 were predicted to affect endothelial dysfunction of ED as autophagy-related hub genes." (PMID 34447638, 2021). "NOTCH1, CDKN2A, and NOS3 are involved in the regulation of endothelial dysfunction and may be potential therapeutic targets for ED by modulating autophagy." (PMID 34447638, 2021). "This study for the first time uncovers that GLI can relieve DR through regulation of endothelial dysfunction, inflammation, and oxidative stress via SIRT1/Notch1 pathway, suggesting that GLI may be an effective agent for the treatment of DR in clinic." (PMID 34961513, 2021).